CCDC116 (coiled-coil domain containing 116)
Synonyms: FLJ36046
Tractability: No criterion of Open Targets' tractability assessment is met for any kind of drug.
Gene: Protein-coding gene on chromosome 22 (21,632,716 to 21,637,329, forward strand). Ensembl gene ENSG00000161180.
Subcellular location: Cytoplasm, cytoskeleton, microtubule organizing center, centrosome
Gene Ontology:
Molecular function: protein binding
Cellular component: centrosome
Genetic constraint (gnomAD): Loss-of-function variants: 24 observed, 29.15 expected, observed/expected ratio (o/e) 0.82, 90% interval 0.6 to 1.16. The upper end of that interval is the gene's LOEUF score, 1.16, which puts it in group 5 of 6, group 1 being the genes least tolerant of losing a copy. Missense variants: 791 observed, 822.63 expected, observed/expected ratio (o/e) 0.96, 90% interval 0.91 to 1.02. Synonymous variants: 298 observed, 339.26 expected, observed/expected ratio (o/e) 0.88, 90% interval 0.8 to 0.97.
Homologues: Orthologues: chimpanzee CCDC116 (98% identical), macaque CCDC116 (92% identical), mouse Ccdc116 (61% identical), rat Ccdc116 (60% identical), dog CCDC116 (58% identical).
Diseases named in the same sentence as CCDC116 in open-access papers:
CCDC116 is named in the same sentence as 4 diseases in open-access papers, as found by Europe PMC text mining. Sharing a sentence is not in itself a finding about the gene and the disease. The quoted sentences say what the papers report.
bipolar disorder (1 paper, 2023). A disorder of the brain that causes unusual shifts in mood, energy, activity levels and the ability to carry out day-to-day tasks. "However, we can identify five top genes at 22q11.2 associated with BMI (YDJC, CCDC116, PPIL2, THAP7, UBE2L3), primarily located outside the canonical CNV region (LCR D-E), three with bipolar disorder (TMEM191B, TUBA8, PPIL2), six with ASD (CLTCL1, AC004471." (PMID 37267418, 2023).
tumor (2 papers, 2024). "The Coiled-Coil Domain-Containing (CCDC) family includes CCDC116, which has been identified as a member implicated in regulating crucial signaling pathways and genes (e.g., PI3K/AKT, ERK/RAS, c-Myc) that are essential for tumor growth, invasion, and metastasis." (PMID 39484038, 2024).
CCDC116 also shares sentences with these, for which no sentence is quoted: cancer (1 paper); cervical cancer (1).